CFTR (CF transmembrane conductance regulator)
Diseases named in the same sentence as CFTR in open-access papers (continued):
Sharing a sentence is not in itself a finding about the gene and the disease.
infection (continued). "We demonstrated that CFTR is present in CF and non-CF macrophages and increases in expression during treatment with CFTR modulators, including a re-organization of CFTR to the peripheral membrane during infection." (PMID 30459435, 2018). "CFTR expression also remained significantly greater in non-CF MDMs during infection compared to CF." (PMID 30459435, 2018). "Thus, we investigated the role of CFTR dysfunction in impaired phagocytosis by pretreating RAW cells with the CFTR172 inhibitor (10 μM) and/or fisetin (20 μM) for 8 hrs followed by PA01-GFP infection with an MOI of 10 for 3 hrs." (PMID 29445254, 2017). "However, in the case of the lung homogenates, although there were more median CFUs in the CFTR–/– than WT homogenates, the difference was not statistically significant for infections with CHB756 or for CHB1126 (data not shown)." (PMID 26469863, 2015). "Lentiviral infection of Caco-2/15 cells, with the same vector carrying a scrambled sequence, neither affected CFTR mRNA (100 ± 24.9 vs. 98 ± 13.7 %, n = 4–16) nor protein expression (100 ± 11.5 vs. 99 ± 11.5 %, n = 4) compared to non-infected cells (data not shown)." (PMID 26549988, 2015). "As expected, Mab infected MDM showed a significant increase in TNF-α at 3 hrs after infection in comparison with uninfected macrophages, and PS-L treatment reduced the levels of the cytokine both in uninfected and infected cells, irrespective of CFTR inhibition." (PMID 39224705, 2024). "We established a fungal epithelial co-culture model to examine the impact of Af infection on CF bronchial epithelial barrier function using Af strains 10AF and AF293-GFP, and the CFBE41o- cell line homozygous for the F508del mutation with (CF+CFTR) and without normal CFTR expression." (PMID 37680748, 2023). "Furthermore, the current study showed that the presence of P. aeruginosa led to an increase in F508del CFTR function upon acute treatment with VX-770, even without the addition of correctors, indicating that infection alone can enhance CFTR’s responses to potentiators." (PMID 37998353, 2023). "The airway epithelium does not passively undergo changes induced by CFTR dysfunction but plays a key role in determining the pathophysiology of CF, characterized by neutrophil-dominated inflammation, ineffective resolution of infection, and irreversible and progressive airway damage." (PMID 36293274, 2022). "Quantitative differences in inflammatory markers have been observed in CF patient serum, tracheal cells, and bronchoalveolar lavage fluid, in the absence of detectable infection, implying that absent CFTR function alone may result in dysregulated immune responses." (PMID 34475490, 2021). "It has been already emphasized that chronic inflammation is a hallmark of CF; inflammation begins early in the disease even in the apparent absence of infection, and it has been postulated that it may be dysregulated in the CF lung as a consequence of defective CFTR." (PMID 29849481, 2018). "Results show that, at 18 hrs post-infection, PS-L induced a more acid phagosomal lumen when compared to untreated controls, in Mab infected MDM, irrespective of CFTR inhibition." (PMID 39224705, 2024). "To evaluate the level of protection offered by CTL-ASL or saline to infection, we studied the effects of ΔfliC and ΔlasR inoculation on the injured area and TEER of the CFTR-CTL and CFTR-KD epithelia, exposed or not to apical hydration." (PMID 35563895, 2022). "However, in the same study, pharmacologic CFTR inhibition did not influence TLR5 expression in non-CF MDMs, suggesting that the loss of TLR5 in CF macrophages may be influenced indirectly by CFTR dysfunction, infection, or through structural changes not recapitulated by channel inhibition." (PMID 35887098, 2022). "A recent study demonstrated that CFTR localizes with LC3-labeled autophagosomes at baseline in normal macrophages and autophagosomes and autophagolysosomes during infection." (PMID 35887098, 2022).
infection (continued). "Finally, the intestine including the rectum is not affected by chronic inflammation, infection with CF pathogens or structural organ damage and remodeling, i.e., factors that may impede CFTR chloride channel function independent of the basic molecular defect of CFTR mutations." (PMID 34066648, 2021). "Finally, while single cell transcriptomic approaches have identified rare but high CFTR expressers in the lung, the ionocyte, it is not yet clear how important it will be to target specific cells within the lung, as each cell type plays an important role in protecting the airways from infection." (PMID 33986686, 2021). "No clear impact of the CFTR inhibitor was observed in cell death or cytokine expression during PA14 and PAO1 infections." (PMID 33664232, 2021). "The lack of bicarbonate secretion due to altered CFTR activity or ATP12A increased expression in CF human airways secondary to inflammation and infection are consistent with a more acidic ASL pH in CF." (PMID 32982730, 2020). "Here, we demonstrate a role for CFTR in the promotion of tertiary lung LF development, B cell BAFF and CXCR4 expression and B cell inflammatory cytokine production in the absence of infection." (PMID 31262295, 2019). "Notably, some remodeling features seem to be somehow CFTR-specific, since delayed and abnormal epithelial regeneration, epithelial thickening, increased reticular basement membrane thickness, and mucus cell number appeared to be independent of infection and inflammation." (PMID 30581723, 2018). "The added advantage of this intervention strategy is that exacerbations in respiratory diseases including those with CFTR dysfunction may be treated and prevented without antibiotics, where multidrug-resistant (MDR) infections are common." (PMID 32847034, 2020). "The CF transmembrane conductance regulator (CFTR) plays a direct role in promoting tertiary lung LF development, B cell activation and B cell inflammatory cytokine production in the absence of infection." (PMID 31262295, 2019). "Additionally, we analyzed TNF-α production from CFTR–/– and WT-mice infected with either highly mucoid CHB756 or non-mucoid CHB1058 at 3 hours and 6 hours post-infection." (PMID 26469863, 2015).
cancer (125 papers, 2011 to 2026). A tumor composed of atypical neoplastic, often pleomorphic cells that invade other tissues. "Evidence indicates that CFTR loss-of-function, in addition to promoting a pro-inflammatory phenotype, is associated with an increased risk of developing cancer, suggesting that CFTR can exert tumor-suppressor functions." (PMID 40029006, 2025). "Future studies should investigate the potential of targeted treatments, such as CFTR modulators and microbiome-modulating therapies, to reduce the cancer risk in this population." (PMID 40563468, 2025). "The results we have presented here support further investigation of CFTR and cancer risk in a larger diverse cohort and will help to inform methods for future analysis." (PMID 41147257, 2025). "The prevalence of somatic cancer risk variants in CFTR PV carriers was compared to that from the COSMIC database." (PMID 41147257, 2025). "There is substantial evidence supporting that cancer predisposition in CF is linked to the role of functional CFTR in maintaining epithelial homeostasis and preventing EMT." (PMID 40910003, 2025). "For these studies, the NGS panel can be used, which includes cancer-associated genes and the CFTR gene." (PMID 37175647, 2023). "Some recent studies assessed the association between carriers of CFTR variants and some pathologies, including cancer risk." (PMID 37175647, 2023). "Another mechanism for increased cancer risk lies in the evidence that the CFTR gene serves as a tumor suppressor gene in the intestinal tract in humans and animal models." (PMID 37374088, 2023). "Although several studies demontrated that F508del mutation is considered a risk factor for developing cancer, the role of CFTR in relation to oncogenesis is unclear." (PMID 36941680, 2023). "The CFTR pathogenic variants carriage was analyzed in patients with malignant neoplasms (1800 samples), in the control group (1825 samples) and among healthy people (10,000 samples)." (PMID 37175647, 2023). "The use of WGS facilitated the analysis of genetic variants in known cancer-associated genes, as well as the evaluation of the frequency and distribution of the CFTR genetic variants with their subsequent comparison with the distribution in the CG." (PMID 37175647, 2023). "Inflammation is a well-established driver of cancer development, and CFTR dysfunction has been associated with elevated levels of inflammation in various tissues." (PMID 37686519, 2023). "A large population-based study involving about 500,000 people assessed the association between carriers of a mutation in the CFTR gene, Phe508del, and the risk of developing 54 types of cancer." (PMID 37175647, 2023). "The aim of this study is to analyze the landscape of germline pathogenic heterozygous CFTR variants in patients with diagnosed malignant neoplasms." (PMID 37175647, 2023). "Obviously, additional studies are needed to assess the clinical significance of the heterozygous carriage of CFTR pathogenic variants in the development of various pathologies in the future, particularly cancer." (PMID 37175647, 2023). "There is increasing interest in the association of cancer incidence with the genetic variation of CFTR." (PMID 36941680, 2023). "CFTR down-regulation has also been associated with poor cancer prognoses, malignancy and metastasis." (PMID 35500936, 2022). "CFTR has been found to act almost exclusively as a tumor suppressor in different cancer types and dysfunctional CFTR has been associated with the promotion of carcinogenesis." (PMID 35743652, 2022). "This review provides an update on the latest research linking CFTR-deficiency to GI cancers, in both CF patients and in sporadic GI cancers, with a particular focus on cancer of the intestinal tract." (PMID 35743652, 2022). "CFTR deficiency is associated with the activation of proinflammatory signaling pathways that can promote cancer development." (PMID 35743652, 2022).
cancer (continued). "Loss of CFTR activity due to either inactivating mutations or via epigenetic silencing has been associated with both cancer initiation and progression, and specifically linked to a wide range of oncogenic phenotypes." (PMID 35743652, 2022). "There have been at least two studies indicating that CFTR acts to prevent proinflammatory pathway activation that is associated with susceptibility to cancers in the biliary tract, such as cholangiocarcinomas." (PMID 35743652, 2022). "We consistently and extensively showed that CFTR induction by 5-Aza-CdR was associated with attenuation of aggressive cancer characteristics." (PMID 32182826, 2020). "Whatever the cause, CFTR downregulation has been reported in cancer tissues and cells from pancreas, prostate, breast, lung and respiratory tract, oesophagus, colon and brain." (PMID 32365523, 2020). "Taken together, our data show that the epigenetic modification of CFTR was associated with cancer activity in HNC." (PMID 32182826, 2020). "Upregulation of CFTR expression has been associated with several cancers such as gastric and ovarian cancers." (PMID 32326161, 2020). "A full account of the association of CFTR mutations or its aberrant expression with the clinical implications in several cancer types is available elsewhere." (PMID 32365523, 2020). "CFTR silencing was closely associated with changes to other cancer-related genes, suppressing apoptosis while enhancing proliferation, cell motility, and invasion in HNC." (PMID 32182826, 2020). "CFTR has been reported to be associated with several cancers, such as cervical cancer, colorectal cancer, prostate cancer and BC." (PMID 32782435, 2020). "Accumulating evidence indicates that aberrant expression or mutation of CFTR is related to carcinoma development." (PMID 32463592, 2020). "Our results show that low expression levels of CFTR are associated with cancer progression and poor survival of NPC patients." (PMID 27769067, 2016). "In turn, there has been recent interest in the risk of various cancers in CF patients and carriers of CFTR mutations." (PMID 27769067, 2016). "There is an increasing interest in the association of cancer incidence with the genetic variations in the CFTR gene." (PMID 25502083, 2015). "This framework is applied to the ABC-B and ABC-C transporter families, which include the drug exporter P-glycoprotein involved in multidrug resistance of cancer cells, as well as the CFTR chloride channel linked to cystic fibrosis disease." (PMID 22590562, 2012). "Future research is needed to conduct such comparisons and to elucidate the specific mechanisms by which CFTR modulators may influence cancer risk in the long term." (PMID 41154689, 2025). "Of the 71 patients with CFTR PVs, two patients had PV in other genes with either an established or possible association with increased cancer risk consisting of the L2357 frameshift variant in BRCA2 (rs80359636) and the Y179C missense variant in MUTYH (rs34612342)." (PMID 41147257, 2025). "Historically, CFTR carrier status has been thought to be benign; however, data are emerging that dysfunction of CFTR may play a role in cancer risk." (PMID 41147257, 2025). "Based on these findings, we hypothesize that FOXI1 and CFTR are not only major regulators of lung ionocytes but also closely associate with CXCL1 cancer subpopulations." (PMID 40568194, 2025). "For the first time in Russia, we evaluated the frequency of CFTR pathogenic variants by whole-genome sequencing in 1800 patients with cancer and compared this with frequencies of CFTR variants in the control group (1825 people) adjusted for age and 10,000 healthy individuals." (PMID 37175647, 2023). "However, concerns have been raised about the potential long-term effects of CFTR modulator therapy on cancer risk." (PMID 37686519, 2023). "In addition, hypermethylation of the CFTR promoter and consequent downregulation have been associated with several cancers, including lung, breast and CRC." (PMID 36765944, 2023).
cancer (continued). "Since HEMT enhances CFTR activity, it is hypothesized that long-term use may reduce cancer risk; however, this remains to be seen as we follow registry data and future comorbidities." (PMID 37374088, 2023). "Although CF primarily affects the respiratory and gastrointestinal systems, evidence suggests that CFTR gene mutations may also increase the risk of specific cancers in CF patients." (PMID 37686519, 2023). "For example, dysfunctional CFTR activity at the intestinal epithelia level can lead to dehydration, promote bacterial overgrowth, which can disrupt the gut microbiome and epithelial turnover, contributing to cancer risk." (PMID 37374088, 2023). "We also explore the impact of CFTR modulator therapies on cancer risk." (PMID 37686519, 2023). "Our patient developed the carcinoma even earlier, suggesting that further molecular alterations might trigger the tumorigenesis in addition to CFTR mutations." (PMID 37046605, 2023). "It will discuss changes in the tissue landscape linked to CFTR-deficiency that may promote cancer development such as breakdowns in physical barriers, microbial dysbiosis and inflammation." (PMID 35743652, 2022). "Owing to the fact that many patients with CF are at a high risk of developing GI cancers, especially CRC, these modulators might prove to be beneficial for the treatment of those cancer patients with specific CFTR mutations." (PMID 35743652, 2022). "The role of CFTR in risk of cancer may change considering the effect of new CFTR modulator therapies on CFTR, and this needs to be investigated in further studies." (PMID 35042562, 2022). "Although effective therapies are now available to treat most CFTR mutations, basic research on CFTR cell biology and its interactions continues to advance our knowledge about this intriguing channel whose function in development and cancer are just starting to be unraveled." (PMID 34947992, 2021). "For example, CFTR —which encodes a member of the ATP-binding cassette transporter superfamily that functions as a chloride channel and controls ion and water secretion in epithelial tissues — decreased from ductal to cancer cells." (PMID 34326696, 2021). "Recent progress in the drug development for CFTR corrector and modifiers with the potential to rescue CFTR function in CF patients may correct the pHi-regulatory dysfunction and reduce cancer risk." (PMID 33553180, 2021). "Other mechanisms may also be the cause of CFTR downregulation in cancer, including altered cell signalling or microenvironment changes within tumours." (PMID 32365523, 2020). "Downregulation of CFTR has also been linked to several known cancer pathways." (PMID 32365523, 2020). "Besides its main function as an anion channel, the CFTR protein has been implicated in epithelial differentiation, tissue regeneration, and, when dysfunctional, cancer." (PMID 32630830, 2020). "How these various alterations in stress responses influence cancer development, particularly in the context of loss of CFTR, remains unclear." (PMID 32326161, 2020). "Our findings demonstrate that CFTR silencing may be associated with cancer progression in HNC and strongly suggest CFTR as a potential tumor suppressor and diagnostic and prognostic biomarker." (PMID 32182826, 2020). "CFTR was shown to upregulate microRNA-193b (miR-193b), a tumor suppressor, after which miR-193b suppressed uPA, frequently associated with malignant traits of cancer development These results suggest that CFTR is responsible for growth restriction." (PMID 32182826, 2020). "Thus, while CFTR has been implicated in the pathogenesis of cancer development, the exact role of CFTR in cancer is still controversial." (PMID 32463592, 2020). "Indeed, various studies have revealed that in a variety of carcinomas, CFTR functions as a tumour suppressor, loss of which promotes the malignant features of cancer cells and cancer development." (PMID 32463592, 2020).